CT45A5 (cancer/testis antigen family 45 member A5)
Synonyms: CT45-5; CT45.5; CT455
Tractability: PROTAC: ubiquitination databases record sites on it.
Gene: Protein-coding gene on chromosome X (135,775,852 to 135,785,503, reverse strand). Ensembl gene ENSG00000228836.
Subcellular location: Nucleus
Subcellular location (Human Protein Atlas): Nucleoli; Nucleoplasm
Gene Ontology:
Cellular component: nucleus
Homologues: Orthologues: rat Ct45a9 (29% identical), mouse Ct45a (28% identical), Caenorhabditis elegans ints-6 (17% identical), Drosophila melanogaster IntS6 (16% identical). Paralogues in human: CT45A6 (100% identical), CT45A7 (100% identical), CT45A3 (99% identical), CT45A1 (99% identical), CT45A2 (98% identical), CT45A8 (98% identical), CT45A9 (98% identical), CT45A10 (95% identical), SAGE1 (35% identical), INTS6L (31% identical), INTS6 (26% identical).
Diseases named in the same sentence as CT45A5 in open-access papers:
CT45A5 is named in the same sentence as 3 diseases in open-access papers, as found by Europe PMC text mining. Sharing a sentence is not in itself a finding about the gene and the disease. The quoted sentences say what the papers report.
endometrial cancer (1 paper, 2021). Primary or metastatic malignant neoplasm involving the endometrium (mucous membrane that lines the endometrial cavity). "Finally, we used immunohistochemistry to investigate the expression of CT45A5 in endometrial cancer tissue." (PMID 33602962, 2021).
cancer (5 papers, 2012 to 2025). A tumor composed of atypical neoplastic, often pleomorphic cells that invade other tissues. "The positive level of CT45A5 in undifferentiated cancer cells in grade 3 (including serous and clear cell histology) was significantly higher than that in the grade 1 group." (PMID 33602962, 2021). "The most up-regulated genes in U87 cells were interleukins and receptors (IL1A, IL13RA2, IL1RN), CT45A5 from the cancer/testis (CT) family of antigens, and the cytoplasmic transporter ATP6V0D2." (PMID 25481245, 2014). "Examples of biclusters from this category include the biclusters consisting of genes from the Cancer-Testis antigens family—MAGEA2, MAGEA3, MAGEA6, MAGEA10, CSAG1, CSAG2, CSAG3 (Xq28)/CT45A3, CT45A5, CT45A6 (Xq26.3)." (PMID 31216036, 2019). "Not surprisingly, several cancer testis antigens (CTA) including CT45A1, CT45A3, CT45A5, CTAG1B and CTAG2 were highly expressed in TNB-High or TMB-High tumors." (PMID 41562064, 2025).
CT45A5 also shares sentences with these, for which no sentence is quoted: tumor (1 paper).